CD4 (CD4 molecule)
Diseases named in the same sentence as CD4 in open-access papers (continued):
Sharing a sentence is not in itself a finding about the gene and the disease.
infection (continued). "In this comprehensive in vivo infection study, we were able to efficiently deplete circulating CD4+, CD8+, and WC1+ γδ T-cell subsets in sheep to investigate their role during BTV infection directly within its natural host." (PMID 38357545, 2024). "We observed that MVC retains a potent antiviral activity when it was administered before the infection in total CD4 cells (> 70% of inhibition) (p < 0.05)." (PMID 38886484, 2024). "In contrast, efficient protection against RSV infection correlates with local cellular immunity in the lungs, such as IFNγ producing CD4+ T-cells, which have been identified as a protective measure against infection and subsequent lung inflammation." (PMID 39472590, 2024). "Mice infected with the high-virulence strain 04–303 showed a rapid and stable increase of CD3+, CD4+, and IL-17A+ cells from Days 3 to 14 after infection." (PMID 39024223, 2024). "From the 15 epitope-specific CD4 T cell responses we identified previously in MCMVSmith infected B6 mice, 14 were detectable in the spleen during the first week of infection upon epitope restimulation." (PMID 38236791, 2024). "During the initial infection, viral gp120 first binds to CD4 on the host-cell surface, leading to a change in its spatial conformation which in turn mediates the interaction of viral glycoprotein 41 (gp41) with host C-C Chemokine Receptor type 5 (CCR5)." (PMID 39086659, 2024). "Frequencies of SARS-CoV-2-specific TNF-alpha+/IFN-gamma+ CD4+ T-cells declined over 12 months after infection (p < 0.01)." (PMID 38940003, 2024). "Meanwhile, the presence of CD4+CD25+ Treg cells in the lip tissue of goats at different stages after infection was detected by fluorescently coupled antibodies." (PMID 38717623, 2024). "The induction of broadly neutralizing responses has previously been associated with factors such as long periods of infection, time to ART initiation, CD4+ T-cell counts, CD4+/CD8+ ratios, and nadir CD4+ T cell counts." (PMID 39460342, 2024). "Past infection was related to the DRB1*16 allele (p: 0.0477), with carriers displaying IgG levels (p: 0.0020), CD4(+) T lymphocyte counts (p: 0.0116) and suggestive CD8(+) T count alterations (p: 0.0602)." (PMID 38933108, 2024). "In mice, the initial stage is the first 10–14 days of infection, before development of antigen-specific CD4 or CD8 T cell responses." (PMID 38701094, 2024). "To test mechanisms of protection induced by lap(−) infections, we investigated the role of CD4+ and CD8+ T cells." (PMID 39103697, 2024). "Consistent with previous findings, we observed a significant increase in the levels of IL-17+ CD4+ T cells from 0.5 to 5 days after infection in the infected mice following the depletion of Ly6G+ neutrophils." (PMID 39703777, 2024). "Untreated HIV leads to the development of acquired immunodeficiency syndrome, which is marked by CD4+ T cell depletion and impaired immune responses to subsequent infections." (PMID 38411080, 2024). "This class switching in humans plus the evidence that CD4 T cells are important for clearance of infection, demonstrates that both humoral and cell-mediated immunity are involved." (PMID 38567021, 2024). "These naïve-like cells express markers associated with naïve T cells but can also express effector T cell molecules; multiple subsets of human naïve-like CD4+ T cells have been described following infection with M.tb and/or vaccination against TB35,36." (PMID 38890283, 2024). "The population of Th1 (CD4+T-bet+) cells, which increased due to infection, was significantly decreased by C1 and C2 administration." (PMID 39081865, 2024). "This is in contrast to the immune‐suppressive profile that is present during infection, which includes increased numbers of CD4 + CD25 + FOXP3 + T cells, antigen‐specific hyporesponsiveness, and distortion of the T cell memory pool." (PMID 39560407, 2024).
infection (continued). "First, the mock-vaccination (MV) group, akin to natural infection, showed high CD4+ TRM cell expression and a significant difference from the other groups after bacterial challenge." (PMID 38276680, 2024). "We observed that infection of cells that transitioned to be long-lived was enhanced among people with a lower nadir CD4+ T cell count." (PMID 38422171, 2024). "The study also discovered that an adaptive immune response using CD4 T cells is crucial for managing the infection, and F11’s ability to bind FcRc improves treatment effectiveness." (PMID 39599888, 2024). "Naïve CD4+ T cells change functionally and phenotypically, enabling primed T cells to proliferate and migrate to the site of infection via the efferent lymphatic vessel and blood." (PMID 39650648, 2024). "In each animal, we calculated differentially expressed (DE) genes between SIV− and SIV+ cells in the two cell types that were the targets of infection, CD4+ T cells, and monocytes." (PMID 38317183, 2024). "Previous studies using the SL3261PYZ97 vaccine have shown that the response to vaccination is limited to the site of infection in the stomach and was reflected in infiltrations of CD4+ T cells, macrophages, and neutrophils." (PMID 38256149, 2024). "Trogocytosed receptors can thus exert complex biological activities on target cells and this process is hijacked by HIV-1 to increase the permissivity of resting CD4 T cells to infection." (PMID 38579727, 2024). "Mtb barcode analysis of samples retrieved at necropsy revealed that previous infection provided enhanced protection against Mtb dissemination of the second infection to lymph nodes, and this protection was partially dependent on CD4+ T cells." (PMID 39214090, 2024). "Animals infected with the low-virulence strain 534 showed a low and stable percentage of CD3+, CD4+, and IL-17A+ lymphocytes during the first and second weeks of infection." (PMID 39024223, 2024). "Longitudinal studies have also demonstrated a rapid activation of SARS-CoV-2-specific cellular immune responses during breakthrough infections, explained both by the recall of CD4+ and CD8+ spike-specific memory cells and de novo T cell responses." (PMID 38932392, 2024). "Of note, PEP-619WW mice exhibited almost twice the frequency of TFH cells among CD4 T cells, as early as 8 days post infection." (PMID 38512979, 2024). "It has to be noted that memory T cell formation cannot be analyzed in mice depleted of CD4+ T cells prior to infection as these mice develop long-term chronic infection." (PMID 39392861, 2024). "Another possibility is a reduced CD4+ T cell count in a transient manner due to prolonged infection, which results in the consumption of these cells." (PMID 39417495, 2024). "CD4+ T cells in mice infected with T. muris, another murine nematode, were shown to react mainly at the site of infection." (PMID 38799456, 2024). "In this study, EN significantly enhanced immune function in GC patients, particularly by increasing CD4+ levels, which was crucial for postoperative recovery and infection resistance." (PMID 39247438, 2024). "Intriguingly, CD4 gene expression was downregulated in all microglial clusters (fold-change ranging from 1.1–1.3) and had the highest expression in Micro-0 during the infection." (PMID 39283947, 2024). "Our study yielded insights into the cellular, molecular, and niche features that support anti-Mtb activity or promote maladaptive immunity following infection—most critically, that CD4+ T cells act as homeostatic regulators of inflammation." (PMID 39214090, 2024). "Many studies using immunization and infection mouse models have shown that CD4+ T cell help is generally required to form functional memory CD8+ T cells." (PMID 39392861, 2024). "In this study, we performed base-resolution whole-genome bisulfite sequencing (WGBS) of primary CD4 + T cells with either HIV-1-Vpr or HIV-1-△Vpr infection, to investigate the role of Vpr in DNA methylation variation." (PMID 38671522, 2024).
infection (continued). "CD39+ DN T-cells were negatively correlated with CD4 T-cell counts and the CD4/CD8 ratio and positively associated with the duration of the infection, whereas CD39+ DN Tregs were negatively associated with the CD4/CD8 ratio." (PMID 39459942, 2024). "Lung CD4+ TRM discretely remodel epithelial cell responses during heterotypic memory-recall infection, which enhance the stability of the CXCL5 transcript via IL-17A and thus accelerate neutrophil recruitment to the lung." (PMID 38632596, 2024). "A gradual decline in the CD4+ T cells was observed in HIV-1-infected mice from an average of 74.6% ± 3.4 before infection to 10.7% ± 3.53 at 40 weeks following infection." (PMID 38399364, 2024). "In individuals with an advanced HIV-1 infection, various mechanisms are responsible for an impaired anti-HIV-1-specific response (including CD4+ and CD8+ T-cells) causing the immune system to get exhausted the longer the infection persists." (PMID 38932203, 2024). "Concerning EBV infection status, when the expression of these cells was compared in the different infection statuses, a significantly higher CD4-GZMB+ cell count was observed in PI patients compared to HC (p = 0.0370)." (PMID 38273012, 2024). "Other studies report LAA to be more likely in those with a lower nadir CD4, and a longer duration of infection." (PMID 38932112, 2024). "Investigations of lesser-known cytotoxic populations, such as γδT-cells, NK T-cells, and cytotoxic CD4+ T-cells are in their infancy and research into the clinical relevance and usefulness of these cell populations during infection are warranted." (PMID 39452664, 2024). "In PWOH and PWH with CD4 counts ≥200 cells/μL, most single-genome spike sequences in each person matched one haplotype that predominated throughout the infection." (PMID 38313289, 2024). "infection remains a major cause of morbidity in HIV-infected people in Ghana, especially those with a suboptimal CD4+ T cell count." (PMID 39597540, 2024). "Together these data demonstrate that the primary mechanism of viral entry and infection of Vδ1 T cells is CD4-dependent." (PMID 39149467, 2024). "QFT which is an upgraded version of IGRA, has been claimed to have a higher efficacy in detecting active infection, as they target both the CD4 and CD8 cells." (PMID 38411377, 2024). "The rate of breakthrough infection was significantly lower in the group of patients with a CD4 cell count < 200 (2.1%)." (PMID 39772116, 2024). "One strategy is to avoid viral attacks into CD4+ cells and thereby prevent infection by blocking the formation of the gp120-CD4 complex." (PMID 38397105, 2024). "Recent work identified PTPN22 itself as a target for the HIV Vpr protein during infection of primary human CD4+ T cells." (PMID 39039893, 2024). "These macrophages can regulate the effector functions of IL-22-producing CD4+ T cells during the late phase of infection." (PMID 39379604, 2024). "Given data indicating that the frequency of IFN-γ+ CD4+ T cells peaked at week 5 post-infection, indicating that the TH1 response was established, we chose this final timepoint for subsequent experiments." (PMID 39076982, 2024). "(B) Bar graphs indicating DRIPc-seq peak counts for HIV-1-infected HeLa cells, primary CD4+ T cells, and Jurkat cells harvested at the indicated hours post-infection (hpi)." (PMID 39630854, 2024). "First, we reconstructed and tested ancestral forms of CD4 at two important nodes in ape speciation, prior to the infection of chimpanzees and gorillas with these viruses." (PMID 38014262, 2024). "Our data and others suggest that this mechanism is far more important in the SG than in other parts of the body, where we found a less pronounced expansion of activated CD4 T cells compared to activated CD8 or NK cells over the course of infection." (PMID 39150988, 2024).
infection (continued). "Analysis of our different mathematical models also indicated that virus-specific CD4+ T cell-mediated clearance of infection had high importance in capturing infection dynamics, appearing in all top-ranked models." (PMID 39575237, 2024). "Using antibodies to deplete T cells before infection, we found that CD4+ and CD8+ T cells play distinct roles in the upper and lower respiratory tract." (PMID 39178263, 2024). "We observed that as CD4+T cell counts declined, the likelihood of multiple infections increased, especially when patients had CD4+T cells <50/μL." (PMID 38774626, 2024). "All measures of intra-host spike gene diversity increased significantly over time among PWH with CD4 counts <200 cells/μL, reflecting longer infections in participants with high initial diversity as well as rising diversity in some participants." (PMID 38313289, 2024). "IL-4 enhances IFN-γ production in the late infection stage, while IL-10 inhibits inflammation and prevents CD4+ T cell-mediated severe immunopathology." (PMID 39597646, 2024). "To evaluate how prior infection and CD4+ T cells modulated neutrophil recruitment and phenotype upon reinfection, we quantified differences in cellular frequencies and gene expression following sub-clustering." (PMID 39214090, 2024). "Overall, these data suggest that mito‐transferred naïve CD4+ T cells from old mice improved control of infection (morbidity and mortality) over non‐manipulated naïve CD4+ T cells from old mice during IAV infection." (PMID 37990641, 2024). "While neutrophils accumulated in the perifollicular spaces, increased numbers of CD4+ T cells were observed in the splenic follicles of mice that received 4x infections." (PMID 38576622, 2024). "HTLV-1 preferentially infects CD4+ T cells and remains in a state of reduced transcription, often being asymptomatic in the beginning of infection, with symptoms developing later in life." (PMID 39459949, 2024). "In contrast, E2 treatment of post-menopausal cells significantly reduced themean infection frequency by 52.4% (from 6.3% to 3.0%) in CD4+ T cells isolated frompost-menopausal patients." (PMID 39872519, 2024). "It is well known that partial depletion of CD4 T cells, around the time of infection of BALB/c mice with a million parasites, results in a stable Th1 response, instead of the usual Th2 response, and so in resistance." (PMID 38611110, 2024). "In the context of human infection, 1–5% of CD4+ T-cells exhibit overduplication of centrosomes possibly contributing to aneuploidy." (PMID 39205287, 2024). "Given that only SN revealed two distinctive populations after infection (SNBright and SN-/Dim), we further characterized them within CD4+ and CD8+ cells." (PMID 39253089, 2024). "Immune memory produced after secondary infection with L. major is important in conferring and maintaining protection through central memory CD4+ T cells." (PMID 39201440, 2024). "As a demonstration of the model utility, we observed significant HIV viral replication in the LN and spleen on day 14 post-infection that corresponded with a decrease in CD4+ T cells in the peripheral blood." (PMID 38693565, 2024). "Nonetheless, we observed a positive correlation between CD4 expression on Vδ1 T cells prior to infection and the proportion of infected cells after seven days of infection with CD4 blockade successfully abrogating infection." (PMID 39149467, 2024). "Major histocompatibility complex (MHC) class II molecules expressed on B cells, monocytes and dendritic cells present processed peptides to CD4+ T cells as one of the mechanisms to combat infection and inflammation." (PMID 38923761, 2024). "Shortly thereafter several mouse models of infection were developed including Ixodes ovatus ehrlichia (IOE) which demonstrated that IFN-γ production by CD4 T cells was essential for resolving infection." (PMID 38567021, 2024).
infection (continued). "Natural regulatory (Foxp3+CD25+CD4+) T cells regulate the production of proinflammatory cytokines during infection, with Foxp3+CD25+CD4+ Tregs promoting IL-10 production." (PMID 39582867, 2024). "CD4+ TEM cells, representing effector memory CD4+ T cells, have received extensive attention in anti-infection research." (PMID 39337460, 2024). "Intravenous infection-mediated HIV transmission leads to initial infection of CD4+ T cells in lymph nodes, the spleen, and GALT." (PMID 39283947, 2024). "The long-term memory phenotype of pp65 and gB-specific CD4+ T cells according to IL-7R expression was more represented in control subjects with remote infection than in pregnant women with primary infection at early and late time points." (PMID 39336935, 2024). "It is likely that this pre-existing immunity or immune imprinting influences the outcome of the CD4+ T cell response induced by S. aureus vaccination and infection." (PMID 39981298, 2024). "During the acute phase of infection, host resistance mainly involves NK cells and CD4+ T cells, while in chronically infected mice, the main cells producing IFN-γ to control the parasite are CD8+ T cells, with a small proportion of CD4+ T cells." (PMID 38038457, 2024). "The T-cells in the liver before infection were primarily effector CD4+ T-cells, effector CD8+ T-cells, NK cells, naïve T-cells, and γδ T-cells." (PMID 39590301, 2024). "The infection of murine alveolar macrophages with modified SARS-CoV-2 pseudovirus also confirmed that M1 polarization exhibited the highest presentation to CD4+ T cells, albeit still lower than its CD8+ T cell presentation level." (PMID 39129565, 2024). "The cytokine environment governs the CD4+ T-cell commitment to become one of various effector T cells both during migration and at the site of infection." (PMID 39650648, 2024). "Here, we used multiparametric flow cytometry and RNA flow fluorescent in situ hybridization (FISH) techniques to characterize cell populations targeted by bNAbs and nnAbs in the context of primary CD4+ T cell infection." (PMID 39373535, 2024). "The CD4+ T-cells were impaired in positive patients compared to patients resolving the infection; in addition, low levels of IFNγ and IL2 were detected in chronic patients." (PMID 39338957, 2024). "In the single infection group, we also found a lower mean CD4+/CD8+ T cell ratio since 15 dpi, while the subsequent samplings at 28 and 35 dpi showed significant decreases on CD4+/CD8+ T cell ratio values." (PMID 38799434, 2024). "The predominant barrier to a cure for HIV-1 is the extremely long-lived CD4+ T cells that possess chromosomally integrated but transcriptionally silent latent provirus that develop over the course of infection." (PMID 39640574, 2024). "Depending on the context of infection, CD4 T cells can differentiate into a variety of Th subsets (Th1/Th2/Th17/pTreg/Tfh) following antigen-specific priming by dendritic cells." (PMID 38271477, 2024). "During infection/challenge, naïve CD4+ T cells differentiate into mature, effector cells which function to clear the challenge, then subsequently differentiating further to memory CD4+ cells." (PMID 39689157, 2024). "Mx1GFP × tgMx1CreRosa26lsl-tdT mice were infected with L.m.-gp66 and assessed for history of IFN signaling (i.e., Mx1 expression) in antigen-specific CD4+ T cells identified using LLO:I-Ab or gp66:I-Ab tetramers on day 7 after infection." (PMID 39321257, 2024). "Vpr is dispensable for HIV replication in most dividing cell lines and has a modest impact on infection of cycling primary CD4+ T-cells in culture." (PMID 39205287, 2024). "aureus infection; however, the introduction of a polyclonal and polyfunctional memory CD4+ T-cell pool significantly reduced the bacterial burden." (PMID 38868766, 2024). "CXCR3 is important for trafficking and recruitment of Th1 and Th17 polarized CD4+ T cells in response to infection." (PMID 38846955, 2024).